GSK3B (glycogen synthase kinase 3 beta)
Diseases named in the same sentence as GSK3B in open-access papers (continued):
Sharing a sentence is not in itself a finding about the gene and the disease.
memory impairment (41 papers, 2012 to 2026). "Several studies have been reported that GSK-3β is excessively activated in the brains of AD patients, and the its activation is associated with memory impairment, synaptic loss, and neuroinflammation." (PMID 38965625, 2024). "Conversely, reducing Akt phosphorylation was associated with GSK-3β activation and ultimately resulted in synaptic plasticity and memory impairment." (PMID 35841005, 2022). "Because decreased Akt and GSK3β phosphorylation have been associated with learning and memory impairment, we investigated the effects of three exposures to 2% isoflurane and 8% desflurane on Akt and GSK3β phosphorylation levels in the hippocampus." (PMID 27057548, 2016). "The classic “GSK-3 hypothesis in AD” proposes that the over-activation of GSK-3β is closely associated with following pathological features including memory impairment, increased Aβ production, Tau phosphorylation and neuronal death." (PMID 32390823, 2020). "Notably, GSK3β is a key kinase for tau phosphorylation, and overactivation of GSK3β is intimately linked to tau hyperphosphorylation, Aβ deposition, plaque-associated microglial-mediated inflammatory responses and memory impairment." (PMID 31801553, 2019). "GSK3β plays an important role in tau hyperphosphorylation, synaptic plasticity impairment, and memory impairment." (PMID 39475992, 2024). "This disruption impedes the activation of the PI3K/AKT pathway, leading to elevated GSK-3β levels, which promotes Aβ accumulation, tau protein tangle formation, neuroinflammation, and memory impairment." (PMID 39766390, 2024). "As our peers emphasized, GSK-3β is a pivotal kinase in AD, and dysregulated CaMKII is a key contributor to memory impairment in neurodegeneration." (PMID 37376018, 2023). "There are several GSK-3β inhibitors have been found to halt AD-mediated pathological events such as tau phosphorylation, Aβ formation, and cognitive and memory impairment, suggesting that GSK-3β inhibitors are the future molecules to treat AD." (PMID 37489441, 2023). "Transfection of a miR-200c inhibitor into the hippocampus of C57BL/6 mice resulted in memory impairment and an increase in p-tau, along with the increase in 14-3-3γ levels and GSK-3β activity." (PMID 35342350, 2022). "The application of PD1-blocking antibody reduced tau hyperphosphorylation and GSK3β activity and prevented memory impairments." (PMID 34977020, 2021). "Upregulation of GSK-3β induces Aβ production and tau hyperphosphorylation, leading to memory impairment." (PMID 34746146, 2021). "Previous study has revealed that GSK-3β accounts for several features of AD such as memory impairment, synaptic failure, Tau hyperphosphorylation and neuronal death." (PMID 32390823, 2020). "Scientific evidence suggests that GSK3B is involved in many pathological hallmarks of AD, including hyperphosphorylation of TAU, increased Aβ production, memory impairment, and neuronal loss." (PMID 29191219, 2017). "Taken together, we propose that post-ischemic prolonged DJS administration ameliorates the memory impairment induced by transient forebrain ischemia via an increase of neurogenesis that is mediated by activation of hippocampal Akt/GSK3β/β-catenin signaling." (PMID 24261472, 2013). "Specifically, GSK3β suppression may significantly reduce Aβ deposition, ultimately resolving spatial learning and memory impairments in transgenic mice with AD." (PMID 40589410, 2025). "Interestingly, the activation of GSK3β is also implicated in amyloidogenesis by inhibiting the secretory cleavage of APP, increasing the production of Aβ and leading to memory impairment in animal models." (PMID 30971876, 2019). "The “GSK3 hypothesis of AD” proposed that the overactivation of GSK3β accounts for several features of this pathology such as memory impairment, tau phosphorylation, increased amyloid production, microglia-mediated inflammation, and neuronal death." (PMID 30090650, 2018).
memory impairment (continued). "There is also the GSK-3β hypothesis which states that it is due to the “over-activity of GSK3β accounts for memory impairment, tau hyper-phosphorylation, increased β-amyloid production and local plaque-associated microglial-mediated inflammatory responses” observed in AD." (PMID 38371416, 2024). "The aberrance in Akt/GSK3β signaling observed in PbA-infected mice may not only be etiologic in the abnormal neuronal profile detected in our model, including tau phosphorylation leading to conformational changes in the protein, but may contribute to the memory impairment demonstrated in these mice." (PMID 23082110, 2012). "The insulin signal pathway of the brain in patients with AD was impaired and the activity of GSK-3β was significantly increased; the activation of GSK-3β in the hippocampus led to phosphorylation of Tau proteins in the T2DM rodent, which further affected memory impairment." (PMID 34867302, 2021). "GluR, Akt and GSK-3β are key factors in this signal transduction pathway and, as demonstrated in the present study, inhibiting 2,6-diisopropylphenol slowed ECT induced hippocampal Tau protein phosphorylation and alleviated spatial learning and memory impairment." (PMID 25998151, 2015). "However, our results indicated transient inhibition of GSK3β activity was not sufficient to resume synaptic ultrastructural alterations, which may explain why the chronic intervention is more effective than acute intervention for recognition memory impairment." (PMID 36949769, 2023).
liver cancer (40 papers, 2012 to 2025). An epithelial or non-epithelial malignant neoplasm that arises from the liver. "Reduced expression of GSK-3β mRNA has been observed in human hepatic cancer linked to HCV infection." (PMID 23606879, 2013). "Elevated expression of GSK-3β diminishes the sensitivity of liver cancer cells to chemotherapeutic agents, thereby playing a substantial role in the development of drug resistance." (PMID 39156976, 2024). "In clinical research, inhibitors targeting the PI3K/AKT/GSK-3β pathway have shown significant potential in treating liver cancer." (PMID 39156976, 2024). "GSK-3β, belonging to the serine/threonine protein kinase family, is crucial in the pathogenesis of liver cancer." (PMID 39156976, 2024). "These elements, notably, have been shown to activate GSK-3β, which in turn promotes the proliferation and metastasis of liver cancer cells." (PMID 39156976, 2024). "Extensive research has established GSK-3β′s pivotal role in the glycolytic processes of liver cancer cells." (PMID 39156976, 2024). "Studies have shown that inhibiting the PI3K/AKT/GSK-3β pathway can reduce aerobic glycolysis in liver cancer cells and promote apoptosis." (PMID 39156976, 2024). "Non-coding RNAs, including miRNAs and lncRNAs, are pivotal regulators of the PI3K/AKT/GSK-3β signaling pathway in liver cancer." (PMID 39156976, 2024). "As a key rate-limiting enzyme in the glucose metabolism pathway, GSK-3β significantly impacts the growth, proliferation, metastasis, and apoptosis of liver cancer cells." (PMID 39156976, 2024). "A recent study has reported that matrine and scopoletin are effective ingredients of the Qinghao–Kushen combination combating liver cancer, which reduce the expression of GSK-3β in HepG2 cells and upregulate GSK-3β in HepG2.2.15 cells." (PMID 38464713, 2024). "Continued research into the activation pathways of GSK-3β holds promise for the development of novel interventions aimed at mitigating the incidence of liver cancer." (PMID 39156976, 2024). "Studies have demonstrated that the suppression of the PI3K/AKT/GSK-3β signaling pathway can increase ROS quantities, thereby yielding significant anti-liver cancer effects." (PMID 39156976, 2024). "In summary, Vinpocetine targets the PI3K/AKT/GSK-3β signaling pathway to suppress liver cancer cell growth." (PMID 39156976, 2024). "We used VOSviewer to create a figure highlighting evaluation of the effect of GSK-3β on liver cancer based on the PI3K/AKT pathway themes, activities, and sources to enhance the review methodology." (PMID 39156976, 2024). "As such, clinical studies focusing on the influence of GSK-3β on the PI3K/AKT pathway show promise in the treatment of liver cancer." (PMID 39156976, 2024). "Plantamajoside showed synergism by increasing metformin cytotoxicity in liver cancer cell lines HepG2 and Huh-7, where it suppressed the activation of Akt/GSK3β signaling." (PMID 36836912, 2023). "A number of studies have shown that the protein kinase B (PKB/AKT)/glycogen synthase kinase‐3β (GSK-3β)/β-catenin pathway plays an important role in the progression of liver cancer." (PMID 36925651, 2023). "The inhibition of GSK-3β activity inhibited liver cancer progression, and this anticancer effect was mainly achieved through the AMPK/mTOR signaling pathway." (PMID 35722140, 2022). "We validated matrine and scopoletin targeting GSK-3β, a key molecule in the treatment of liver cancer." (PMID 35722140, 2022). "When it physically interacts with GSK3β to phosphorylate β-catenin, a well-characterized oncogene in liver cancer, the degradation of β-catenin is triggered to promote the growth of liver cancer cells." (PMID 34445958, 2021). "Other studies found that SHP2 and β-catenin proteins can form a complex and SHP2 increased β-catenin accumulation by inhibiting glycogen synthase kinase 3β (GSK-3β)–mediated β-catenin degradation in liver cancer." (PMID 33898435, 2021).
liver cancer (continued). "Further studies revealed that β-catenin-370aa can act as a decoy for GSK3β to protect β-catenin from GSK3β-mediated degradation and thus indirectly promote liver cancer growth." (PMID 34461958, 2021). "Studies have shown that the inhibition of GSK-3β lowers the level of nuclear Nrf2 through nuclear export and degradation of Nrf2 in liver cancer cells and improves cell survival during the later phases of oxidative stress." (PMID 31011401, 2019). "SHP-2 increases β-catenin accumulation by inhibiting glycogen synthase kinase 3β (GSK3β)-mediated β-catenin degradation in liver cancer stem cells to enhance the self-renewal of liver cancer stem cells." (PMID 29558404, 2018). "Recent studies suggested that GSK3β can promote the invasion of pancreatic, lung, breast and liver cancer cells, and inhibition of GSK3β induces apoptosis." (PMID 26213494, 2015). "The activation of GSK-3β has been identified as a key factor in the development of liver cancer." (PMID 39156976, 2024). "Consequently, deciphering the mechanisms by which GSK-3β activation fosters liver cancer progression is essential for devising effective preventive strategies." (PMID 39156976, 2024). "9-ING-41 is a GSK-3β inhibitor being tested in a Phase 1/2 clinical trial as a single agent and combined with chemotherapy in patients with refractory hematologic malignancies or solid tumors, including liver cancer." (PMID 39156976, 2024). "A key factor in the onset and progression of liver cancer is the PI3K/AKT/GSK-3β signaling pathway." (PMID 39156976, 2024). "For example, circβ-catenin could encode a novel β-catenin isoform, called β-catenin-370aa, which competitively interacts with GSK3β and promotes tumour growth via the Wnt/β-catenin pathway in liver cancer." (PMID 38105235, 2023). "The results suggested that HA-ADT could reduce the expressions of p-AKT, p-GSK-3β, and p-β-catenin in human liver cancer cells." (PMID 36925651, 2023). "In liver cancer, circβ-catenin produces a novel isoform of β-catenin with the length of 370-amino acids (β-catenin-370aa), and β-catenin-370aa can prevent full-length β-catenin degradation from GSK3β to thus promote activation of the Wnt-pathway." (PMID 35931993, 2022). "HBV-X protein upregulated β-catenin with an inactivation of GSK-3β in liver cancer." (PMID 23606879, 2013). "Programmed Cell Death 6 (PDCD6): Enhances proliferation, migration, and invasion capabilities of liver cancer cells via activation of the AKT pathway, leading to GSK-3β phosphorylation." (PMID 39156976, 2024). "Our previous study has suggested that Py infection inhibits PI3K/Akt/GSK-3β/Snail signaling pathway and therefore inhibits EMT in a murine liver cancer model." (PMID 37916167, 2023). "Through cellular function experiments, the study verified that PPARδ could stimulate liver cancer cell proliferation, migration, and angiogenesis by activating the PI3K/AKT/GSK-3β signaling pathway." (PMID 39156976, 2024). "Consequently, targeting of GSK-3β, particularly within the PI3K/AKT signaling pathway, is regarded as a promising therapeutic strategy for liver cancer." (PMID 39156976, 2024). "The scarcity of consolidated and accessible summaries of research on the impact of various drugs and compounds targeting GSK-3β within the PI3K/Akt pathway, specifically in the context of liver cancer, has posed challenges in information retrieval and synthesis." (PMID 39156976, 2024). "Furthermore, DHA also inhibits GRB2 and GSK3β, genes which are downstream in the ERBB signaling pathway found in our liver cancer meta‐analysis and known to promote multiple types of cancers." (PMID 37859621, 2023). "Considering that activated AKT may also contribute to increased c-MYC stability by suppressing GSK-3β activity, we hypothesized that c-MYC might contribute to the DEN-induced liver cancer phenotype observed in the Ppp2r5d HE and HO mice." (PMID 37627221, 2023).
liver cancer (continued). "To further address the role of Aldob in the regulation of Akt phosphorylation in HCC, we generated stable Aldob-overexpressing liver cancer cell lines Huh7 and LM3 and found that ectopic expression of Aldob resulted in a marked reduction of Akt, GSK3β, and S6K phosphorylation levels." (PMID 33275593, 2020). "Generally, WNT signaling activation disrupts the binding of Glycogen synthase kinase 3 beta (GSK3β) to β-catenin to allow the later to translocate to the nucleus and activate target gene transduction, including ZEB1, but several other molecules can modulate this cascade in liver cancer." (PMID 41303618, 2025). "Notably, GSK3β-mediated phosphorylation of SETD3 is a prerequisite for FBXW7β-dependent ubiquitination and protein degradation of SETD3, thereby attenuating its oncogenic role in the proliferation of liver cancer cells." (PMID 38272222, 2024).
mood disorder (40 papers, 2011 to 2026). A cognitive disorder a disturbance in which the person's mood is hypothesized to be the main underlying feature. "These were GSK3β, Akt, and Erk1/2—the proteins that are components of intracellular signaling pathways implicated in mood disorders." (PMID 41226527, 2025). "Polymorphisms in the GSK3B locus have been previously reported to be associated with AD and mood disorders." (PMID 39337715, 2024). "Decreased GSK3β phosphorylation, which causes increased GSK3β activity in specific cellular locations, pathways, and circuits, promotes susceptibility to mood disorders, and GSK3β inhibition is therapeutic for mood disorders." (PMID 37580315, 2023). "Neuroimaging genetic studies of mood disorders have reported associations between GSK3β variation and hippocampal volume." (PMID 30310078, 2018). "Since high levels of GSK-3β activity are generally associated with mood disorders, the underlying mechanisms of the bi-phasic concentration dependence become important." (PMID 29163047, 2017). "Our study focused on GSK-3β, another upstream signaling molecule of CREB-BDNF, because GSK-3β is involved in various signaling systems and is possibly associated with mood disorders." (PMID 26798520, 2015). "Overall, changes in the regulation of GSK3β activity have been associated with the actions of several psychoactive drugs, including those affecting 5-HT functions in the treatment of mood disorders." (PMID 22826345, 2012). "In this regard it is notable that GSK3B has been implicated in the pathophysiology of mood disorders." (PMID 23075086, 2012). "GSK3β is a multifunctional serine/threonine protein kinase involved in the modulation of various aspects of neuronal function and dysregulation of this kinase has been implicated in mood disorders." (PMID 34121997, 2021). "Several neurogenetics studies have investigated associations between GSK3β and mood disorders." (PMID 30310078, 2018). "GSK3β gene studies have shown that some polymorphisms may underlie the susceptibility to mood disorders and may serve as potential markers of severity of such disorders." (PMID 23449817, 2012). "Lithium, a potent GSK‐3β inhibitor with therapeutic potential for mood disorders, neurodegenerative diseases, and viral infections, faces challenges in clinical use due to its narrow therapeutic window and toxicity at high doses." (PMID 41020548, 2026). "The pattern of drug-induced changes in phosphorylation of GSK3β, Akt, and Erk1/2—key components of intracellular signaling pathways involved in mood disorders—varied by gender." (PMID 41226527, 2025). "The present study has identified HSPA12A as a stabilizer of mood and behavior to alleviate mood disorders by maintaining GSK3β-mediated glycolysis in hippocampal neurons and thus cerebral lactate homeostasis." (PMID 37580315, 2023). "Recently, several signalling molecules, especially glycogen synthase kinase-3β (GSK-3β), have been explored as possible candidate targets for the treatment of AD, PD, and mood disorders." (PMID 38107562, 2023). "A growing evidence points to GSK-3β as a pro apoptotic molecule and its dysfunction is correlated to the pathophysiology of mood disorders." (PMID 35943710, 2022). "Future studies investigating the effects of EPO on different cellular networks mediated by GSK3β are highly warranted to identify its common and specific roles in the treatment of mood disorders and other neuropsychiatric illnesses." (PMID 30310078, 2018). "The aim of this review is to describe the potential importance of glycogen synthase kinase 3-beta (GSK3β) as a multi-potent molecular mechanism of EPO-induced hippocampal volume change in mood disorder patients." (PMID 30310078, 2018). "The identification of more GSK3β substrates is therefore of great importance for understanding the larger impact GSK3β plays in hippocampal volume of individuals with mood disorders." (PMID 30310078, 2018).